BTNL2 (butyrophilin like 2)
Diseases named in the same sentence as BTNL2 in open-access papers (continued):
Sharing a sentence is not in itself a finding about the gene and the disease.
ulcerative colitis (7 papers, 2013 to 2025). An inflammatory bowel disease involving the mucosal surface of the large intestine and rectum. "In a demonstrative example, BTNL2 exhibited associations with well-established IMDs phenotypes (asthma and Behcet’s disease) and novel ones (celiac disease and ulcerative colitis [UC])." (PMID 39009607, 2024). "Polymorphism in the human BTNL2 gene has been linked to inflammatory disorders such as sarcoidosis, ulcerative colitis (UC), rheumatoid arthritis and myositis 12, 13, 14, 15, 16, and to prostate cancer." (PMID 27957327, 2016). "Therefore, it would be interesting to check for the consequences of the CNV in diseases associated with polymorphisms in BTN and BNTL genes, e.g. BTNL2 in Crohn’s disease or ulcerative colitis." (PMID 23829304, 2013). "Despite conflicting opinions, the 6p21.3 region carrying HLA and BTNL2 genes is still considered to be associated with an increased risk of TH1/TH17 diseases (tuberculosis, leprosy, beryllium disease, ulcerative colitis, or Crohn disease)." (PMID 27914482, 2016). "Common variants at the BTNL2 locus, have been previously shown to be associated with ulcerative colitis whilst being independent of the nearby known HLA susceptibility alleles." (PMID 25671699, 2015).
inflammatory bowel disease (6 papers, 2011 to 2018). A spectrum of small and large bowel inflammatory diseases of unknown etiology. "Like the B7 protein family, many human and murine BTNL members have been shown to control T lymphocytes response, and polymorphisms in human BTNL2 have been linked to several inflammatory diseases, such as pulmonary sarcoidosis, inflammatory bowel disease and neonatal lupus." (PMID 23829304, 2013). "The strong LD is particularly important in relation to the neighboring HLA-DQ genes and HLA-DRB paralogs, but it is also difficult to formally exclude an association with the nearby BTNL2 gene, which has been associated with inflammatory bowel disease, or even genetic variants further away." (PMID 21413052, 2011). "Intriguingly, BTNL2 is primarily expressed in the small intestinal epithelium and appears to function as a negative regulator of T-cell activation, with mutations in this protein conferring increased risk of inflammatory bowel disease (IBD)." (PMID 29867962, 2018).
psoriasis (5 papers, 2009 to 2025). An autoimmune condition characterized by red, well-delineated plaques with silvery scales that are usually on the extensor surfaces and scalp. "Further stratified association analysis illustrated that HLA-C∗06:02 and NOTCH4:G511S contribute to the family aggregation of psoriasis, and BTNL2:R281K specifically confers risk for SP." (PMID 33134369, 2020). "Second, vitiligo and psoriasis share some common susceptibility genes (e.g., IFIH1, BTNL2) and genetic loci (e.g., HLA-C/HLA-B rs9468925)." (PMID 40156617, 2025). "For example, in psoriasis, new associations of HLA-DPB1 and BTNL2 genes and five loci among HLA-C, -B, -DPB1, and BTNL2 were reported using NGS." (PMID 30410504, 2018).
colitis (4 papers, 2015 to 2023). Inflammation of the colon. "Dextran sulfate sodium (DSS)-induced colitis in BTNL2-KO mice enhances inflammation and delays mucosal repair in the colon, highlighting the role of BTNL2 in regulating inflammatory signals." (PMID 37407551, 2023). "During DSS-induced colitis, Btnl2-KO mice exhibit increased inflammation and delayed mucosal repair in the colon." (PMID 34312491, 2021). "Briefly, cohoused Btnl2-KO and WT littermates were subjected to DSS-induced colitis by administering DSS for 7 days followed by 8 days of water." (PMID 34312491, 2021).
Crohn disease (4 papers, 2013 to 2021). A gastrointestinal disorder characterized by chronic inflammation involving all layers of the intestinal wall, noncaseating granulomas affecting the intestinal wall and regional lymph nodes, and transmural fibrosis. "Genes that were significant with at least two variables include: BTNL2 for alopecia areata, NOD2 for Crohn’s disease, PLA2R1 for membranous neuropathy, LMO1 for neuroblastoma, and TNPO3, UBE2L3, HLA-DRA, and HIC2 for systemic lupus erythematosus." (PMID 26170196, 2015).
lung adenocarcinoma (4 papers, 2015 to 2023). A carcinoma that arises from the lung and is characterized by the presence of malignant glandular epithelial cells. "However, BTNL2 (rs3817963) was reported as a new susceptibility locus of lung adenocarcinoma as well, the most common histologic type of lung neoplasm in the Japanese population." (PMID 26253105, 2015). "Patients with lung adenocarcinoma and colon adenocarcinoma that expressed low levels of BTNL2 had significantly improved survival compared to those expressing high levels of BTNL2." (PMID 35017553, 2022). "This also suggests that inhibition of BTNL2-dependent γδT17 cell accumulation holds therapeutic potential in human lung adenocarcinoma, as well as in other γδT17-enriched cancer types." (PMID 35017553, 2022). "In unaffected tissue adjacent to cancerous lesions, expression of BTNL2 was significantly decreased compared to that observed in lung adenocarcinoma and colon adenocarcinoma lesions, which is quite similar to the expression pattern of PD-L1." (PMID 35017553, 2022). "Next, we analyzed in detail the pattern of BTNL2 expression in lung adenocarcinoma." (PMID 35017553, 2022). "Importantly, ~38% of lung adenocarcinoma samples had medium-to-high levels of BTNL2 expression, but low levels of PD-L1 expression." (PMID 35017553, 2022). "In lung adenocarcinoma samples, BTNL2 was mainly expressed by cancer cells." (PMID 35017553, 2022). "The abundance of γδT17 cells in freshly isolated lung adenocarcinoma samples was also significantly higher than in para-cancerous samples, and, importantly, protein levels of BTNL2 were much higher in almost all of the examined cancer samples when compared to matched para-cancerous tissue." (PMID 35017553, 2022). "Additionally, we found that BTNL2 expression reliably mirrored the expression of Napsin A, which is a well-established biomarker for lung adenocarcinoma." (PMID 35017553, 2022). "Four loci, 5p15.33 (TERT), 6p21.3 (BTNL2), 3q28 (TP63) and 17q24.2 (BPTF), previously shown to be strongly associated with overall lung adenocarcinoma risk in East Asians, were re-discovered as loci associated with a higher susceptibility to EGFR mutation-positive lung adenocarcinoma." (PMID 27501781, 2016).
asthma (3 papers, 2020 to 2024). "The results from the Asian population replicated 16 associations (including BTNL2-asthma), and the Black population replicated 7 associations (including RNF5-celiac disease)." (PMID 39009607, 2024). "At present, no research about BTNL2 gene polymorphism and asthma has been reported locally and internationally." (PMID 31605414, 2020).
autoimmune disease (3 papers, 2009 to 2024). A disorder resulting from loss of function or tissue destruction of an organ or multiple organs, arising from humoral or cellular immune responses of the individual to their own tissue constituents. "Functional variant rs2076530 of the BTNL2 gene was identified conferring susceptibility to the autoimmune diseases T1D, RA, and SLE (G allele was linked to T1D and RA, and the A allele associated with SLE)." (PMID 26253105, 2015). "The regulatory function of BTNL2 on T cell proliferation may explain the possible association of this gene variant with inflammatory and autoimmune diseases, including AA." (PMID 39459398, 2024). "While this relationship has been previously established for rs2076530 in BTNL2 in a subset of the autoimmune diseases, we systematically identify all such SNPs which are significantly associated with at least one disease per class." (PMID 20041220, 2009).
celiac disease (3 papers, 2021 to 2024). An autoimmune genetic disorder with an unknown pattern of inheritance that primarily affects the digestive tract. "As BTNL2 modulates gastrointestinal homeostasis and the identified HLA alleles regulate the gastrointestinal tract in celiac disease, it is proposed that the data on ASD risk may be linked to genetically regulated gut inflammatory processes." (PMID 37407551, 2023). "Diminished expression of BTNL2 may dysregulate ileal γδ IELs, with consequent intestinal inflammation, whilst overexpression of the celiac disease-associated HLA-DQA1*05 or other pro-inflammatory HLA alleles will further contribute to inflammation." (PMID 37407551, 2023).
leprosy (3 papers, 2013 to 2021). Leprosy is a chronic infectious disease affecting primarily the skin and peripheral nervous system. "A study of leprosy in Indian population showed that BTNL2-DRA intergenic SNPs confer risk for leprosy." (PMID 34976012, 2021). "According to authors, the combination of low T-cell inhibition status of BTNL2, less inhibition of TNF by BAT1, and low TNF expression may provide protection from leprosy, which may be stronger in the presence of high TNF producer allele genetic background." (PMID 23936864, 2013).
lymphoma (3 papers, 2021 to 2025). A malignant (clonal) proliferation of B- lymphocytes or T- lymphocytes which involves the lymph nodes, bone marrow and/or extranodal sites. "Using exome sequencing, they identified six recurrent, rare, and potentially deleterious variants within 5 kb of lymphoma-associated GWAS loci in 75 MM cases (BTNL2, EOMES, TNFRSF13B, IRF8, ACOXL, TSPAN32)." (PMID 41300981, 2025). "Furthermore, coinhibition/immune checkpoint receptor (CI/ICR) B7-H4 overexpression promotes LIUS-upregulated IGs in lymphoma cells and LIUS-downregulated IGs in BM cells, while CI/ICR BTNL2 overexpression inhibits LIUS-upregulated IGs." (PMID 33628851, 2021).
multiple sclerosis (3 papers, 2009 to 2024). A progressive autoimmune disorder affecting the central nervous system resulting in demyelination. "For instance, the G allele of rs2076530 in BTNL2 predisposed patients to RA, AS, and type 1 diabetes, but may play a protective role instead in multiple sclerosis and autoimmune thyroid disease." (PMID 28054948, 2017).
schizophrenia (3 papers, 2015 to 2021). A major psychotic disorder characterized by abnormalities in the perception or expression of reality. "Three human genes, ADCYAP1, PSORS1C2, and BTNL2, are associated with neuronal phenotypes, such as schizophrenia." (PMID 34542594, 2021). "The chromosome conformation capture (3C) analysis in human brain cells revealed the architecture of multipoint chromatin interactions between the schizophrenia-associated genetic and epigenetic polymorphic sites and distantly located HLA-DRB5 and BTNL2 genes." (PMID 31624234, 2019). "First, BTNL2 lies within the extended MHC region of chromosome 6, a schizophrenia-associated locus that is gene dense and spans several million bases." (PMID 26633303, 2015). "Given a previous report (in this set of trios) of a de novo nonsense mutation in this gene on a proband with schizophrenia, at face value, BTNL2 might be considered an attractive candidate imprinted gene for schizophrenia." (PMID 26633303, 2015).
systemic lupus erythematosus (3 papers, 2009 to 2015). An autoimmune multi-organ disease typically associated with vasculopathy and autoantibody production. "BTNL2 has been associated with RA, systemic lupus erythematosus, and type 1 diabetes; this is attributed to its association with predisposing HLA DQB1-DRB1 haplotypes, which may explain its presence in our data as well." (PMID 20018027, 2009).
autoimmune’ disorders (2 papers, 2016 to 2023). "As well as the modulation of T-cell-related properties, BTNL2 may also modulate HLA class II allele expression, with consequences for immune/’autoimmune’ disorders." (PMID 37407551, 2023).
breast carcinoma (2 papers, 2020 to 2022). "BTNL2, BTNL3, BTNL8, BTNL9, and SKINTL constitute the BTNL family, which regard as a tumor inhibitor in many cancers, such as malignant melanoma and breast cancer." (PMID 36034784, 2022).
colorectal cancer (2 papers, 2022 to 2023). A primary or metastatic malignant neoplasm that affects the colon or rectum. "BTNL2 polymorphisms are associated with susceptibility to lung adenocarcinoma, and γδT17 cells have been reported to play key roles in human colorectal cancer (CRC) progression through recruitment of MDSCs23." (PMID 35017553, 2022). "Thus, it is becoming evident that BTNL2 possesses an immunoregulatory role, which is likely critical in the progression of some malignancies, including colorectal cancer, where it has been demonstrated that BTNL-2 ablation in these mice reduced tumorigenesis by downregulating IL-22 production." (PMID 37240071, 2023).
rheumatoid arthritis (2 papers, 2015 to 2021). A chronic, systemic autoimmune disorder characterized by inflammation in the synovial membranes and articular surfaces. "The SNP rs28362678 on BTNL2 has previously been shown to be associated with rheumatoid arthritis, and gene function related to diabetes." (PMID 34201265, 2021). "Additional coding and loss-of-function variants in BTNL2, have been associated with susceptibility to other immune related disorders including adult-onset sarcoidosis and rheumatoid arthritis." (PMID 25671699, 2015). "While these studies examined different SNPs of the same genes not included in our dataset, the SNP rs28362678 (BTNL2) identified in our study as having different variants for resettlers and native Germans has been shown to be associated with rheumatoid arthritis." (PMID 34201265, 2021).
rosacea (2 papers, 2018 to 2020). A chronic erythematous skin disorder that affects the face. "The study identified an association between rosacea risk and a single nucleotide polymorphism (SNP) in the human leukocyte antigen (HLA) region located between HLA-DRA and BTNL2, which supported the concept of an inflammatory genetic component to rosacea." (PMID 29771307, 2018). "Finally, shared genetic risk loci between rosacea and IBD such as HLA-DRB1*03:01 and butyrophilin-like 2 (BTNL2) could be another explanation for this association." (PMID 33182618, 2020).
vitiligo (2 papers, 2016 to 2025). Generalized well circumscribed patches of leukoderma that are generally distributed over symmetric body locations and is due to autoimmune destruction of melanocytes. "Variants in BTNL2 may play a role which involved in vitiligo susceptibility versus vitiligo age of onset." (PMID 26870082, 2016).
colonic adenocarcinoma (1 paper, 2022). "A similar anti-tumour effect was also found following i.p. injection of BTNL2 mAb into CT26 (murine colonic adenocarcinoma) or A20 (murine B cell cancer) tumour-bearing mice." (PMID 35017553, 2022).
coronary atherosclerosis (1 paper, 2015). Atherosclerosis of the coronary vasculature. "According to thedata of a genome–wide study,variations in BTNL2 are also associated with the developmentof coronary atherosclerosis." (PMID 26483964, 2015).
glioma (1 paper, 2022). A benign or malignant brain and spinal cord tumor that arises from glial cells (astrocytes, oligodendrocytes, ependymal cells). "Because the basal expression levels of BTN1A1, BTNL2, BTNL3, and BTNL8 were relatively low, in further analysis, we only focused on the expression of BTN2/3 subfamilies in pan-gliomas." (PMID 36033440, 2022).
Hepatitis (1 paper, 2022). Inflammation of the liver. "Key HLA-DRB1-DQB1 haplotypes and role of the BTNL2 gene for response to a hepatitis B vaccine." (PMID 35360730, 2022).
hepatocellular carcinoma (1 paper, 2022). A malignant tumor that arises from hepatocytes. "In 25 out of 27 hepatocellular carcinoma samples, the pattern of PD-L1 expression (relative expression in cancer vs. para-cancerous tissue) generally reflected the pattern of BTNL2 expression." (PMID 35017553, 2022).
Lofgren’s syndrome (1 paper, 2023). "Some HLA, MHC2TA, BTNL2, CCR2, CCR5, TNF, and ANXA gene polymorphisms are associated with an acute presentation of sarcoidosis—Lofgren’s syndrome, whereas other polymorphisms in these genes are implicated in non-Lofgren’s syndrome." (PMID 37511027, 2023).
malaria (1 paper, 2020). Malaria is a serious and sometimes fatal disease caused by a parasite that commonly infects a certain type of mosquito which feeds on humans. "Overexpression of inhibitory molecules such as PD-1, LAG-3, or BTNL-2 on antigen-experienced T cells in malaria-infected patients were suggested as possible mechanisms accounting for the impaired development of effective and long-lasting adaptive immunity." (PMID 33519801, 2020).
myocardial infarction (1 paper, 2021). Gross necrosis of the myocardium, as a result of interruption of the blood supply to the area, as in coronary thrombosis. "In a sensitivity analysis, we performed a GWAS excluding self-reported cases of previous myocardial infarction (20 resettlers, 66 native Germans); the same SNPs from BTNL2 and TGFBR3 marked a genetic difference between the resettlers and native Germans." (PMID 34201265, 2021).
prostate neoplasm (1 paper, 2015). A neoplasm (disease) that involves the prostate gland. "Furthermore, there were new results implicating BTNL2 as a novel prostate neoplasm-related gene." (PMID 26253105, 2015).
ST Elevation Myocardial Infarction (1 paper, 2026). A myocardial infarction that produces elevation in the ST segments of the ECG. "Through targeted whole-genome sequencing and replications in sex-specific cohorts with ST-elevation myocardial infarction (STEMI) or non-ST-elevation myocardial infarction (NSTEMI) we discovered a novel haplotype in the butyrophilin-like 2 (BTNL2) gene that predisposes men to NSTEMI." (PMID 41928795, 2026).